ZNF576 (zinc finger protein 576)
Description:
May be involved in transcriptional regulation.
Synonyms: MGC2508
Tractability: No criterion of Open Targets' tractability assessment is met for any kind of drug.
Gene: Protein-coding gene on chromosome 19 (43,596,392 to 43,601,189, forward strand). Ensembl gene ENSG00000124444.
Subcellular location: Nucleus
Subcellular location (Human Protein Atlas): Golgi apparatus; Nucleoplasm
Gene Ontology:
Molecular function: protein binding; DNA-binding transcription factor activity
Biological process: regulation of DNA-templated transcription
Cellular component: nucleus
Genetic constraint (gnomAD): Loss-of-function variants: 7 observed, 10.15 expected, observed/expected ratio (o/e) 0.69, 90% interval 0.39 to 1.29. The upper end of that interval is the gene's LOEUF score, 1.29, which puts it in group 5 of 6, group 1 being the genes least tolerant of losing a copy. Missense variants: 191 observed, 242.71 expected, observed/expected ratio (o/e) 0.79, 90% interval 0.7 to 0.89. Synonymous variants: 88 observed, 93.46 expected, observed/expected ratio (o/e) 0.94, 90% interval 0.79 to 1.12.
Homologues: Orthologues: chimpanzee ZNF576 (100% identical), macaque ZNF576 (97% identical), dog ZNF576 (85% identical), pig ZNF576 (79% identical), guinea pig ZNF576 (76% identical), rabbit ZNF576 (69% identical), zebrafish plagl2 (25% identical), Drosophila melanogaster CG12391 (23% identical), Drosophila melanogaster hb (20% identical), Caenorhabditis elegans Y5F2A.4 (19% identical), zebrafish plagx (17% identical), Caenorhabditis elegans hbl-1 (9% identical). Paralogues in human: ZKSCAN2 (28% identical), ZSCAN29 (26% identical), ZSCAN32 (26% identical), ZNF274 (25% identical), ZNF18 (25% identical), ZNF202 (25% identical), ZNF444 (24% identical), ZSCAN5B (23% identical), PLAG1 (22% identical), ZSCAN5A (22% identical), PLAGL2 (22% identical), ZNF496 (22% identical), and 17 more.
Diseases named in the same sentence as ZNF576 in open-access papers:
ZNF576 is named in the same sentence as 1 disease in open-access papers, as found by Europe PMC text mining. Sharing a sentence is not in itself a finding about the gene and the disease. The quoted sentences say what the papers report.
COVID-19 (1 paper, 2023). A disease caused by infection with severe acute respiratory syndrome coronavirus 2. "When analyzing the DEGs using the bioinformatic platform Enrichr-KG, the most relevant transcription factors potentially driving the differences in kidney gene expression between COVID-19 AKI and non-COVID-19 AKI were POLR2L, EIF3K, BOLA3, RFXANK, and ZNF576." (PMID 38003268, 2023).